RNU6-1109P (RNA, U6 small nuclear 1109, pseudogene)
Gene: Small nuclear RNA gene on chromosome 3 (190,165,417 to 190,165,523, reverse strand). Ensembl gene ENSG00000212489.
Homologues: Orthologues: chimpanzee U6 (100% identical), macaque U6 (95% identical), guinea pig U6 (70% identical), pig U6 (64% identical), mouse Gm56216 (64% identical), rat U6 (64% identical), rabbit U6 (61% identical). Paralogues in human: RNU6-854P (80% identical), RNU6-1190P (79% identical), RNU6-1081P (79% identical), RNU6-1152P (79% identical), RNU6-1227P (79% identical), RNU6-393P (79% identical), RNU6-836P (79% identical), RNU6-1131P (78% identical), RNU6-144P (78% identical), RNU6-16P (78% identical), RNU6-181P (78% identical), RNU6-211P (78% identical), and 1284 more.